DHRS4L1 (dehydrogenase/reductase 4 like 1 (pseudogene))
Description:
Putative oxidoreductase.
Synonyms: SDR25C4; SDR25C4P
Gene: Transcribed unprocessed pseudogene on chromosome 14 (24,036,501 to 24,050,968, forward strand). Ensembl gene ENSG00000225766.
Diseases named in the same sentence as DHRS4L1 in open-access papers:
DHRS4L1 is named in the same sentence as 2 diseases in open-access papers, as found by Europe PMC text mining. Sharing a sentence is not in itself a finding about the gene and the disease. The quoted sentences say what the papers report.
cancer (1 paper, 2020). A tumor composed of atypical neoplastic, often pleomorphic cells that invade other tissues. "CHRNB4 was also associated with long noncoding RNA, such as DHRS4-AS1, DHRS4L2, DHRS4L1, and SMAD5-AS1, which functions by affecting the proliferation, invasion (epithelial-mesenchymal transition), cell cycle progression and the apoptosis of cancer cells." (PMID 33304845, 2020).
DHRS4L1 also shares sentences with these, for which no sentence is quoted: neuroblastoma (1 paper).